GPC1 (glypican 1)
Diseases named in the same sentence as GPC1 in open-access papers (continued):
Sharing a sentence is not in itself a finding about the gene and the disease.
tumor (continued). "Isolated tumour cells were assayed via immunocytochemistry with monoclonal mouse anti-glypican-1 (anti-GPC-1) antibody MIL-38 (Minomic International Ltd., Sydney, NSW, Australia) previously reported to be highly specific and sensitive in the detection of PCa." (PMID 31905736, 2019). "In agreement with the increase in tumor growth in mice injected with GPC-1 shRNA PC-3 cells, MMP-9 protein expression was higher in these tumors as compared to controls." (PMID 31391540, 2019). "The demonstration that GPC-1 inhibition enhanced PC-3 tumor growth is in direct contrast to the in vitro data." (PMID 31391540, 2019). "In contrast, in vivo GPC-1 appears to act as tumor suppressor, possibly by mediating extracellular signaling and cancer cell interaction with the TME." (PMID 31391540, 2019). "The microchannel proved to be functional in at least 79% of cases for capturing GPC1+ putative tumour cells from the urine of patients with localised PCa." (PMID 31905736, 2019). "We determined the effect of GPC-1 inhibition on tumor growth by subcutaneously implanting PC-3 cells transfected with either GPC-1 shRNA or scrambled shRNA into 6–8 week old male athymic nude (NCr, nu/nu) mice." (PMID 31391540, 2019). "Unfortunately, this limits our studies in vivo to identify the effect of GPC-1 in DU-145 cells on tumor growth in vivo." (PMID 31391540, 2019). "Results were confirmed by immunohistochemical analysis in 10 human tumor cases and 10 normal matched mucosa specimens, revealing a strong increase of membrane/cytoplasmic staining for GPC1 in 80% of tumors." (PMID 30027065, 2018). "This is unsurprising as GPC1 has been shown to enhance proliferation and migration in vitro, and promote tumor growth, angiogenesis, and invasion in mouse models of PDAC." (PMID 29721179, 2018). "As PDAC cells invade the surrounding stroma, this allows release of GPC1, leading to mitotic stimulation and tumor progression." (PMID 29721179, 2018). "TEM revealed that GPC1+ exosomes from tumour tissue, plasma of CRC patients and supernatant of HT‐29 and HCT‐116 cells exhibited similar round‐shaped membrane vesicles with diameters of 30–90 nm." (PMID 28233416, 2017). "The growth of xenograft HT‐29 and HCT‐116 tumours increased plasma GPC1 protein levels while overexpression of miR‐96‐5p and miR‐149 in xenograft tumours significantly decreased plasma GPC1 protein levels in mice." (PMID 28233416, 2017). "We further provided evidence for the secretion of GPC1 positive exosomes from CRC tumour cells in vitro and in vivo." (PMID 28233416, 2017). "Cytometry assay showed a significant higher percentage of GPC1+ exosomes in CRC tumour tissues than that in the normal colon tissues (P < 0.001)." (PMID 28233416, 2017). "The percentage of GPC1+ exosomes in tumour tissues is about fourfold higher than that in the normal tissues." (PMID 28233416, 2017). "Western blot showed that GPC1 protein level in tumour exosomes was significantly higher than that in normal colon tissue exosomes (P < 0.001)." (PMID 28233416, 2017). "Cell-surface expression of gpC1 in a panel of tumor cell lines was also characterized by a glycan-specific flow cytometry assay." (PMID 28490841, 2017). "Anti-GPC1 mAb strongly inhibited tumor growth via antibody-dependent cellular cytotoxicity dependent and independent manner in GPC1-positive ESCC xenograft models." (PMID 28445969, 2017). "Western blot showed that both AdmiR‐96 and AdmiR149 virus injection significantly inhibited GPC1 protein expression in the HT‐29 tumour tissues." (PMID 28233416, 2017). "An anti-tumor glycan monoclonal antibody (mAb) C1 served as a key reference reagent for monitoring tumor cell-surface expression of gpC1." (PMID 28490841, 2017). "Previous studies have observed the roles of GPC1 in tumour growth and angiogenesis 5, 6, 7 through promotion of FGF‐FGFR activation and signalling." (PMID 28233416, 2017).
tumor (continued). "NOD/SCID mice, known to have low natural killer cell activity and no CDC activity and functional B and T cells, were used to assess the contribution of ADCC and CDC to the anti-tumor effect of anti-GPC1 mAb." (PMID 28445969, 2017). "Ability of anti-α3(V) antibodies to slow WT/PyMT tumour growth suggests α3(V) as a potential target for therapeutic treatments of human tumours in which α3(V)-GPC1 interactions contribute to cell growth." (PMID 28102194, 2017). "In contrast, α3(V) and GPC1 co-localize in mouse WT/PyMT, and human luminal and basal-like, tumours." (PMID 28102194, 2017). "Consistent with a previous report 11, this study observed GPC1 overexpression in CRC tumour tissues." (PMID 28233416, 2017). "The changes in miR‐96‐5p and miR‐149 correlated with the changes in GPC1 protein expression and GPC1+ exosomes from the tumour tissues and plasma of CRC patients." (PMID 28233416, 2017). "We also demonstrated that anti-GPC1 mAb (clone 1–12) induced marked tumor growth inhibition in GPC1-positive human ESCC xenograft models." (PMID 28445969, 2017). "The percentage of GPC1+ exosomes and the GPC1 protein expression in exosomes from tumour tissues and plasma of CRC patients before surgical treatment was significantly elevated compared to that in the peritumoural tissues and the plasma of healthy controls." (PMID 28233416, 2017). "Anti-GPC1 mAb induced significant tumor growth inhibition in ESCC xenograft models via antibody-dependent cellular cytotoxicity (ADCC) and complement-dependent cytotoxicity (CDC) dependent and independent manner." (PMID 28445969, 2017). "In this study, we observed a loss of miR‐96‐5p and miR‐149 expression in the tumour tissues and plasma of CRC patients and GPC1 positive exosomes from CRC tumour tissues and plasma of CRC patients before surgical treatment." (PMID 28233416, 2017). "Next, we also assessed the anti-tumor effect of anti-GPC1 mAb against ESCC patient tumor-derived xenograft (PDX) model (designated ESCC-8)." (PMID 28445969, 2017). "Western blot showed that plasma GPC1 protein levels in mice bearing HCT‐116 tumours were significantly increased compared to the healthy mice (P < 0.001)." (PMID 28233416, 2017). "Anti-GPC1 mAb significantly inhibited the growth of the ESCC-8 PDX compared with isotype control mouse IgG2a (67.87% ± 6.28% tumor growth inhibition at day 31) and also tumor weight." (PMID 28445969, 2017). "We produced chicken/mouse chimeric mAb against human GPC1, which cross-reacts with mGPC1, and demonstrated marked tumor growth inhibition by anti-GPC1 mAb in SCID mice xenografted with GPC1-positive TE14 cells via ADCC and CDC activity." (PMID 28445969, 2017). "Since anti-GPC1 mAb specifically target GPC1 positive tumor cells, we consider that anti-GPC1 mAb would be quite effective therapy for treatment of ESCC cells which remain after cisplatin therapy." (PMID 28445969, 2017). "In the present study, we identified exosomes in the plasma and tumour tissues, which exhibited enriched GPC1 protein level in CRC patients for the first time." (PMID 28233416, 2017). "Cytometry assay showed that both AdmiR96 and AdmiR149 virus injection significantly decreased the percentage of GPC1+ exosomes in the plasma of mice bearing HT‐29 tumours (P < 0.001)." (PMID 28233416, 2017). "This study confirmed a high GPC1 expression in CRC tumour tissues compared to the normal colon tissues (P < 0.001)." (PMID 28233416, 2017). "Both AdmiR‐96 and AdmiR149 virus injection significantly decreased the plasma GPC1 protein levels in mice bearing HT‐29 tumours." (PMID 28233416, 2017). "We are currently conducting studies evaluating the anti-tumor efficacy of anti-GPC1 mAb in xenograft models using cancer types other than ESCC." (PMID 28445969, 2017). "Immunofluorescence showed GPC1 to be present in both WT/PyMT and KO/PyMT tumours, and to co-localize with α3(V) in the former." (PMID 28102194, 2017).
tumor (continued). "Our previous study also demonstrated that GPC1+ exosomes were significantly increased in both the plasma and the tumor tissues of CRC patients, however, the clinical significance of GPC1+ exosomes in CRC patients has not yet been elucidated." (PMID 29254156, 2017). "In this study, we investigated the level of GPC1 positive exosomes and the expression of miR‐96‐5p, miR‐149 and miR‐182‐5p in tumour tissues and plasma of CRC patients before and after surgical treatments." (PMID 28233416, 2017). "Anti-GPC1 mAb also inhibited tumor growth of GPC1 positive ESCC patients derived tumor xenograft models." (PMID 28445969, 2017). "Both AdmiR‐96 and AdmiR149 virus injection significantly decreased the plasma GPC1 protein levels in mice bearing HCT‐116 tumours." (PMID 28233416, 2017). "On this basis, our data on Glypican-1 and Glypican-3 dysregulation are of high interest, as they can help depict a more comprehensive picture of Wnt signal modulation in the tumor microenvironment." (PMID 26517809, 2015). "The molecular and immunohistochemical analysis performed in our human CRC set revealed very similar results, indicating the significant association of GPC1 over-expression and GPC3 under-expression in tumor lesions with respect to the normal colon mucosa." (PMID 26517809, 2015). "Levels of GPC1 crExos correlate with tumour burden and the survival of pre- and postsurgical patients." (PMID 26316886, 2015). "Enhanced expression of GPC1 in the stromal compartment of these lesions also closely correlated with tumour recurrence and paralleled the more predictable prognostic implication of tumour staging." (PMID 25935541, 2015). "GPC1 overexpression has been described in certain tumors, although with some peculiarities depending on the neoplasia." (PMID 24570896, 2014). "Analogously to syndecan 2, glypican 1 expression was analyzed by immunohistochemistry using tumor tissue arrays." (PMID 24570896, 2014). "GPC1 expression correlated well with tumor grade, and showed some degree of positive relationship with patient survival, which suggests it has possible uses as a prognosis factor." (PMID 24570896, 2014). "Activation of these pathways is crucial for tumor establishment and development and lead to specific modulation of HSPGs, such as syndecans-2 and -4 and glypican-1, in addition to other ECM-modulating molecules." (PMID 23984412, 2013). "Our results showed the expressions of all the proteoglycans as well and extended the list with glypican-1 expression in prostate epithelial cells and tumour stroma." (PMID 23691363, 2013). "GPC1 was highly expressed in HCC tumour tissues, which was verified by qRT‐PCR." (PMID 39823268, 2025). "Moreover, discrepancy between the in vitro and in vivo data (GPC1 inhibition increased PC-3 tumor size in mice xenografts) was suggested to be possibly mediated by stromal cells in the tumor microenvironment." (PMID 41470114, 2025). "Furthermore, this research elucidates the role of extracellular GPC1 in enhancing cancer cell motility, thus contributing to tumor progression." (PMID 39300946, 2024). "With regard to the effect of anti-GPC1 mAb treatment on tumor burden, although the mean total lung weights in the 10 mg/kg and 50 mg/kg anti-GPC1 mAb groups were decreased by 28% and 14% as compared with those of the control group, the differences were not statistically significant (P > 0.05." (PMID 38966167, 2024). "We think these results may be due to the fact that plasma GPC1 concentration is affected not only by the tumor but also by vascular endothelial damage or other host factors." (PMID 39300946, 2024). "The relative number of colonies [colony area (%)] and percent of well area covered by colonies [colony area (%)] were determined to quantify the inhibitory effect of anti-GPC1 mAb on tumor cell survival and proliferation under the anchorage-independent condition." (PMID 38966167, 2024).
tumor (continued). "Univariate analysis indicated that the residual tumor (p < 0.001), tumor size ≥30 mm (p = 0.027), lymphatic invasion (p = 0.007), pT factor ≥2 (p = 0.046), pN factor ≥2 (p < 0.001), pStage ≥3 (p = 0.012), and high GPC1 concentration (p < 0.001) were correlated with poor overall survival." (PMID 39300946, 2024). "In vitro and in vivo experiments have demonstrated that restoring the expression levels of miR-96-5p and miR-149 inhibits GPC1 expression and the secretion of GPC1-positive exosomes, leading to reduced cell viability, increased cell apoptosis, and suppressed tumor growth." (PMID 38298209, 2024). "The results showed that GPC-1 mRNA level was significantly (P < 0.05) elevated in the HCC samples compared with the normal group (normal n = 50, tumor n = 371), and GPC-1 showed significantly higher mRNA levels in stage 3, and there is a potential increase as the cancer progresses." (PMID 38982153, 2024). "Moreover, results of the Western blot analysis of tumor samples indicated that the short-term anti-GPC1 mAb treatment had little effect on the activity of the MEK/ERK/RSK and Akt/GSK3/mTOR pathways." (PMID 38966167, 2024). "One study investigating glypican-1 (GPC1)-targeting CAR T cells demonstrated that the anti-tumor effects observed in immunodeficient mice may be hampered by the development of GvHD." (PMID 39335157, 2024). "In addition, the level of GPC-1 crExos correlated with tumor load and the survival of patients before and after surgery, suggesting that GPC-1 has the potential to serve as a reliable biomarker for monitoring treatment efficacy and prognosis." (PMID 38254825, 2024). "Extracellular GPC1 protein plays a role in both tumor cell motility and cancer progression." (PMID 39300946, 2024). "Further, detection and quantification of GPC1 by histopathological and immunohistochemical methods in tumor biopsies could be a new way to predict the biological outcome." (PMID 36944188, 2023). "Importantly, the levels of GPC1+ crExos were found to correlate with tumor burden and patient survival both before and after surgery." (PMID 38201485, 2023). "Based on the human tissue tumor and cell-line data described earlier, we hypothesized that since GPC-1 is upstream of PI3K/Akt overexpressing GPC-1 should theoretically increase PI3K/Akt expression." (PMID 37649964, 2023). "Tumor growth suppression was observed in PANC-1 mice after the administration of [211At]GPC1 mAb." (PMID 37827841, 2023). "Additional work demonstrated that GPC-1 knockout mice also had anti-tumor growth activity." (PMID 38203714, 2023). "Attempt to reveal the mechanism through which downregulation of GPC1 leads to attenuation of tumor growth using systematic Ingenuity Pathway Analysis indicate that suppression of GPC1 results in ECM-mediated inhibition of specific pro-cancer signaling pathways involving TGF-β and p38 MAPK." (PMID 36944188, 2023). "GPC-1 overexpression has been demonstrated in up to 47% of CCA tumor specimens." (PMID 38203714, 2023). "Anti-GPC1 monoclonal antibodies have been utilized to develop an antibody-drug-conjugate (ADC), immunotoxin, bispecific T-cell engager (BiTE), and CAR T cells against GPC1-positive tumor cells and their antitumor efficacy has been demonstrated in preclinical models." (PMID 37031249, 2023). "Moreover, the levels of GPC-1+ crExos were correlated with tumor burden and survival in patients before and after surgery, suggesting the potential of GPC-1 serving as a reliable biomarker for treatment effect and prognostic monitoring." (PMID 35180868, 2022). "Taken together, these findings suggest that GPC1 may function as a tumor promoter in CRC cells through promoting TGF-β signaling pathway." (PMID 35671267, 2022). "Other analyses found that GPC1 may be involved in CRC development through influencing intestinal tumor hypoxia on immune cells in the tumor microenvironment." (PMID 35671267, 2022).
tumor (continued). "In addition, compared with that in paracarcinoma tissues, the protein expression of GPC1 in tumour tissues was elevated." (PMID 35671267, 2022). "Another limitation is that only one tumor marker of glypican 1 was tested." (PMID 35991837, 2022). "RT-qPCR was performed to detect the GAPDH and the tumor marker of glypican 1 gene expression." (PMID 35991837, 2022). "Here, detection or enrichment may be possible by tumor-specific markers such as glypican-1 or using immune-enrichment." (PMID 35205822, 2022). "Our findings have broad implications for the role of GPC1 as a key molecule in tumor progression." (PMID 35348113, 2022). "Similarly, an anti-GPC1-antibody was used to decorate gold nanoparticles which also carried a natural antibacterial, anti-inflammatory, anti-tumor tetracycline diterpenoid compound, oridonin, as well as gadolinium (Gd) and Cy7 dye." (PMID 34249755, 2021). "Moreover, the GPC1+ exosome level is indicative of tumor stage and distant metastases, and its low levels are related to increased survival." (PMID 33803470, 2021). "Glypican-1 (GPC1), a common lipid-anchored membrane protein on sEV, is overexpressed in a variety of solid tumors and may influence tumor progression." (PMID 34094979, 2021). "Furthermore, GPC1 knockdown by shRNA has been shown to have markedly decreased proliferation in tumor cells in the presence of the a3(V) chain." (PMID 33742285, 2021). "Recently, the cell surface proteoglycan glypican-1 (GPC1) on tumor exosomes was identified." (PMID 35582309, 2021). "This lack of specificity for tumor type does not in principle limit the use of GPC1-exosomes as an early pre-diagnostic, also suitable for screening for patients warranting further investigation." (PMID 34249755, 2021). "A recent study has reported GPC1 enrichment in tumor-derived exosomes." (PMID 33737938, 2021). "Furthermore, the levels of GPC-1 expressing exosomes were closely related to the tumour burden and the survival of patients before and after tumour resection." (PMID 34680372, 2021). "Type V collagen which is upregulated in human breast cancer, also appears to be involved in cancer cell proliferation, as the ablation of the α3 chain of collagen V in MMTV-PyMT mouse model inhibits tumor progression by reducing glypican-1-dependent tumor cell proliferation." (PMID 34298680, 2021). "Furthermore, qRT-PCR analysis revealed that SLC2A3, FOXO3, EGFR and GPC1 were upregulated in tumor samples." (PMID 33962639, 2021). "Our objective in this work is to elucidate further the role of GPC1 in this menacing tumor." (PMID 32180897, 2020). "Although it is still uncertain whether GPC1 protein expression is completely negative in normal tissues of human, our anti-GPC1 mAb (clone: 1–12) specifically recognizes GPC1 protein expressed on tumor cells and is suitable for the generation of CAR-T cells." (PMID 32228854, 2020). "Furthermore, GPC1-specific CAR-T cell therapy enhanced antitumor responses of TIL against non-GPC1 endogenous tumor antigens." (PMID 32228854, 2020). "These mice showed a significant growth inhibition of the inoculated mGPC1-negative tumors, indicating the induction and involvement of T cells specific for endogenous tumor antigens in the strong antitumor effects of GPC1-specific CAR-T cell therapy in the syngeneic tumor modes." (PMID 32228854, 2020). "In our study, tumor-specific killing by our CAR-T cells may be explained by a tumor-specific recognition by the anti-GPC1 mAb (clone: 1–12)." (PMID 32228854, 2020). "GPC-1 expression was significantly related with tumor dedifferentiation and diameter." (PMID 32206189, 2020). "Hence, in the present study, we further investigated the expression of glyco-epitope gpC1 in tissue microarrays from BCA patients who had different histological tumor types classified at various pathological stages." (PMID 32879924, 2020).